PARP1 (poly(ADP-ribose) polymerase 1)
Diseases named in the same sentence as PARP1 in open-access papers (continued):
Sharing a sentence is not in itself a finding about the gene and the disease.
cancer (continued). "Since PARP1 is involved in the repair of modified bases, ssDB and dsDB, blocking the ADP-ribosylation activity with small molecules, can achieve synthetic lethality with DNA damaging agents in the treatment of cancer." (PMID 24970148, 2012). "Since the use of PARP1 inhibitors in cancer treatment is still in an experimental phase, the long-term effects of PARP1 inhibition have not yet become apparent." (PMID 22184287, 2011). "It was also hoped that a global view of the PARP-1, PARP-2 and PARG interactomes may help to grasp the ramifications of cancer treatment by PARP inhibitors, either in terms of therapeutic efficiency or side effects." (PMID 20388209, 2010). "The co-expression of HELLS and PARP1 in multiple cancer types is significant and implies that HELLS might cooperate with PARP1 in regulating various aspects of DDR and/or DNA damage tolerance, promoting cancer cell proliferation and survival despite the elevated DNA damage." (PMID 41297801, 2025). "Given their current exploration as therapeutic targets across diverse conditions, including cancer, metabolic disorders, and neurodegenerative models, an in-depth investigation of the mutual pathways they navigate holds significant promise for enhanced understanding of the SIRT1/PARP1 axis." (PMID 38397799, 2024). "The observed synergy between the PEGylated PARP1 inhibitor talazoparib (PEG~TLZ) and the DNA alkylating agent temozolomide (TMZ) may lead to improved therapeutic strategies for patients with this challenging cancer." (PMID 38893160, 2024). "Taken together, this emergence of PARP1 and other members of the ART family in the regulation of immune pathways underscores the immense potential for the further exploitation of these enzymes not only in cancer therapy but also in the treatment of immune-mediated diseases." (PMID 39062190, 2024). "We monitored the molecular state of PARP-1 via Western blot and investigated whether proteolytic processing and characteristic PARP-1 cleavage fragments indicative of apoptosis could be observed when bacteria and cancer cells were co-cultured." (PMID 37559137, 2023). "We may suppose that tumour cells can hijack PARP-1 activity to promote DNA repair, and therefore cancer progression, without activating cell death pathways which are often defective in these cancers." (PMID 37686260, 2023). "Furthermore, it was shown that cancer cell lines lacking BRCA1/2 were sensitive to inhibitors of PARP1, whereas cells with functional BRCA1/2 were not." (PMID 37190285, 2023). "The designed PARylated PARP1-antibody-MMAF conjugate could potentially kill HER2-expressing cancer cells in high specificity, potentially improving the physicochemical and pharmacological properties of cancer therapy." (PMID 37177365, 2023). "The function of PARP1 in gene regulation thus may contribute to the establishment of the molecular actions of PARP inhibitors for their clinical applications in treatment of inflammatory diseases, as well as, cancer." (PMID 36077699, 2022). "To examine whether the absence of RUNX1 in the cancer cells affects cancer cell-driven hepatocyte modifications in vivo, we stained specimens that were generated from our previous publication with PARP-1, ARP2/3, or E-cadherin antibody." (PMID 35267627, 2022). "Therefore, PARP-1 inhibitors are successfully used in cancer therapy and serve as a paradigm for the development of a novel generation of drugs exploiting the principle of synthetic lethality." (PMID 36323657, 2022). "Also the in silico studies proved that the docking score of the compound suggests the interaction of the compound which could tightly regulate key target genes controlling cancer like ER, EGFR kinase, EGFR-cSRC, HDAC-2, PARP-1 and BRAF." (PMID 35059624, 2022).
cancer (continued). "Therefore, inhibition of PARP1/2 results in genome instability that destroys cancer cells while allowing non-malignant cell survival." (PMID 36533080, 2022). "To date, PARP1 inhibitors target the catalytic domain; however, other mechanisms of PARP1 pathway inhibition might offer promise for therapeutic intervention in cancer as well as non-oncogenic diseases." (PMID 35203571, 2022). "Additionally, ALC1 (amplification in liver cancer-1) plays an important role in metastasis and invasion of BC, and poly(ADP-ribosyl)ated PARP1 stimulated ALC1 at DNA damage sites, emphasizing that the PBZ sphere of CHFR and PMD and Macro spheres of ALC1 are essential for the PAR interface." (PMID 36685928, 2022). "Therefore, the inhibitors of PARP1 or POLQ block Alt-EJ pathway and kill HR-defective cancer cells." (PMID 35281059, 2022). "Notably, high mRNA expression levels of PARP1 proximal proteins that are recruited to stressed replication forks correlated with the sensitivity of cancer cells to PARP-trapping inhibitors but not to non-trapping inhibitors." (PMID 36350633, 2022). "Hence, inhibition of PARP1 and the related enzyme PARP2 could be a better therapeutic approach to target specific DNA repair pathways in cancer." (PMID 36338767, 2022). "Poly(ADP-ribose) polymerases-1 (PARP-1) are involved in DNA repair damage and so PARP-1 inhibitors have been used as potentiators in combination with DNA damaging cytotoxic agents to compromise the cancer cell DNA repair mechanism, resulting in genomic dysfunction and cell death." (PMID 35424391, 2021). "Interestingly, the role of the DNA repair gene (PARP1) in therapy resistant cancers also has not been studied and explored well." (PMID 34199353, 2021). "Thus, we next determined whether olaparib, a small molecule PARP1/2 inhibitor, restores BIN1 levels in the CDDP-R cancer cell lines." (PMID 34948122, 2021). "Elevated nuclear PARP1 expression in patients without nodal metastases strongly correlated with significantly shorter disease-free survival (p = 0.0015) and revealed a trend with shorter cancer-specific overall survival (p = 0.05)." (PMID 33572647, 2021). "Thus, we hypothesized that, in spontaneously cisplatin-resistant cancer (CDDP-R) cell lines, endogenous PARP1 activity is required for stimulating MYC activities." (PMID 34948122, 2021). "D2O-induction of apoptosis has been documented before in a variety of cultured cancer cell lines, involving modulation of apoptotic executioners (such as BAX and BCL2) and markers (including PARP-1 cleavage) through unknown upstream mechanisms responsive to D2O exposure." (PMID 33546433, 2021). "Poly(ADP-ribose) polymerase (PARP) enzymes (numbering seventeen in total) have drawn considerable attention as drug targets in the last decade owing to the clinical success of non-selective PARP1/2 inhibitors Olaparib, Talazoparib, Niraparib and Rucaparib approved for cancer treatment." (PMID 34482781, 2021). "Summing up, the decrease in PARP1 activity and ADP-ribosylation with inhibitors in cells such as macrophages, which directly impact cancer progression and may support current anticancer approaches and improve cancer treatment." (PMID 32900001, 2020). "In addition to playing an important role in DNA repair, PARP-1 is involved in other biological processes, such as chromatin remodeling, transcriptional regulation, hypoxic response, angiogenesis, epithelial-mesenchymal transition (EMT), and cancer meta-stasis." (PMID 32122376, 2020). "Compensatory mechanisms of restoring fork protection in the absence of BRCA1/2 or PARP1 may be at play in PARP inhibitor-resistant cancers." (PMID 32029455, 2020).
cancer (continued). "We show that APE2 mRNA expression is positively correlated with PCNA, APE1, XRCC1, PARP1, Chk1, and Chk2 across these 6 tumor tissue types; however, groupings of other DNA repair and DDR genes are correlated with APE2 with different patterns in different cancer types." (PMID 32111912, 2020). "Due to the fact that possible inhibition of IDO1 by specific inhibitors would decrease NAD+ in human cancer cells and that NAD+ is crucial for PARP1 activity, we hypothesize that double-hit therapy of IDO1 and PARP1 inhibitors would be a promising combination treatment." (PMID 32380691, 2020). "Finally, our results showed that PDAC cancer stem cells were more sensitive to the FGFR1 inhibitor PD173074 in the absence of PARP1 in vivo." (PMID 32276472, 2020). "Likewise, there was no significant relation between rs1136410 and PARP1 activity of 19 human cancer cell lines." (PMID 33112558, 2020). "Understanding the immunomodulatory roles of PARP-1 and PARP-2 may provide invaluable clues for the rational development and exploitation of more selective anti-cancer PARP inhibitor drugs, both as new monotherapeutic approaches and in combinations with immunotherapy." (PMID 32046278, 2020). "Such induced lethality is not observed in XRCC4 single knockout cells or XRCC4/PARP1 doubly deficient cells, leading us to hypothesize that Pol θ might represent a promising target for killing NHEJ-deficient cancer cells exposed to G1 DNA damage." (PMID 33067475, 2020). "The topic of PARP1 inhibitors in cancer will not be discussed in detail in this review." (PMID 30991935, 2019). "Altogether, these data show that PARP-1 genetic KO was not conclusive in respect to the inhibitory/promoting effect on cancer development, probably depending on the multifaceted role of PARP-1 in DNA repair and inflammation with possible opposite effects on tumor initiation and tumor promotion." (PMID 31877876, 2019). "Additionally, PARP-1 inhibition in vivo can reverse PAH in two models and PARP-1 inhibitor Olaparib is now being explored in clinical trials as a potential PAH therapy following success in cancer trials (ClinicalTrials.gov identifier NCT03251872)." (PMID 31868216, 2019). "Furthermore, we identified phenanthrenes acting as PARP1 inhibitors that efficiently eradicate a variety of human cancer cells without impairing benign cells." (PMID 31692907, 2019). "Poly(ADP-ribose)ylation (PARylation) by PAR polymerase 1 (PARP1) and PARylation removal by poly(ADP-ribose) glycohydrolase (PARG) critically regulate DNA damage responses; yet, conflicting reports obscure PARG biology and its impact on cancer cell resistance to PARP1 inhibitors." (PMID 31827085, 2019). "Similarly, the energy status of proliferating cells demands a high ATP concentration; thus, the NAD+/NADH redox ratio determines, for example, that PARP1 activity is five times higher in cancer cells than in normal, non-transformed cells." (PMID 31614656, 2019). "Therefore, “dual pathway synthetic lethality” simultaneously targeting PARP1 and RAD52 offers a promising and very aggressive therapeutic approach against HR-compromised tumors, allowing for more robust elimination of cancer cells and preventing the emergence of drug resistance." (PMID 31615159, 2019).
cancer (continued). "Our identification of linker histone H1.2 as a novel PARP1 downstream target may help us better understand the functional mechanisms of ATM inhibition in cancer treatment and may lead to the discovery of new promising targets for cancer therapy." (PMID 29844578, 2018). "Importantly, western blotting demonstrated PARP-1 cleavage, indicating active apoptosis, only in cancer cells but not in normal human diploid fibroblasts (NHDF) after protoporphyrin IX treatment." (PMID 30603043, 2018). "Taken together, the data demonstrate that the inhibition of PARP1 by inhibitors and by specific siRNAs blocks the interaction of the PARP1/Ku70/Ku80 complex with genes containing ALCDs, resulting in a repression of ALCD and subsequent inhibition of proliferation of cancer cells." (PMID 30271949, 2018). "Notably, we also found that IFN-α promoted cancer cell survival as evidenced by higher colony number of IFN-α-treated cells in a clonogenic survival assay (quantitative results, lower panel) and reduced apoptotic cleavage of PARP-1." (PMID 29587825, 2018). "The increased levels of PARP-1 mRNA in the cancer and Ca&AD groups might indicate a protective role of PARP-1 in these cells and thus explain the increased resistance to death in lymphocytes from patients with a history of cancer." (PMID 29472838, 2018). "Given the role of EMT in metastasis, and macroH2A1.1’s role in inhibiting PARP-1 activity, our findings could provide insight into understanding EMT progression, and potentially provide a new mechanism as to how macroH2A1 expression affects cancer progression." (PMID 29339820, 2018). "Moreover, as Tdp1 and PARP1 are necessary for cancer cell survival, their inhibitors may also be effective against HPV-induced cancer." (PMID 28182794, 2017). "Therefore, we hypothesized that PARP1 and FOXO3A may interact together and play critical roles in cancer progression." (PMID 26540566, 2015). "According to this discrepant result, we hypothesized that PARP1 expression by oncogenic stimuli may induce FOXO3A expression to attenuate cancer progression as a negative feedback." (PMID 26540566, 2015). "Cancer-derived cells express an abnormally high level of the PARP-1 protein and no PARG." (PMID 24504413, 2014). "Furthermore, without PARylation activity, PARP-1 cannot regulate Ets-1 protein levels, nor counteract the genotoxicity of ROS production and prevent cancer cell death." (PMID 23405229, 2013). "In cancer treatment with PARPi, the personalization of therapy is important because many factors can influence the efficiency of PARPi, such as HR and NHEJ status, PARP-1 levels or its activity and finally other factors that influence intracellular concentrations of PARPi." (PMID 23450678, 2013). "As the disruption of PARP-1 or PARG activity leads to the uncoordinated metabolism of PAR, this phenomenon may be required for enhancing the chemo-therapeutic treatment of specific types of cancers." (PMID 23254695, 2013). "As reviewed above, inhibition of PARP1 activity may also have a dramatic effect on RBP-related post-transcriptional processes, providing both a new frontier for cancer treatment and concomitant pitfalls, which should be examined to avoid adverse effects on patients." (PMID 23921685, 2013). "It was first demonstrated by two teams that two individually non-lethal conditions, i.e., PARPi-mediated inhibition of PARP-1 and BRCA mutation-induced HRR deficiency in cancer cell, would become synthetic lethal when combined in a single cell [reviewed in Ref." (PMID 24294592, 2013). "To validate the hypothesis that PARP1 elevation is reflective of an increased dependency on DNA repair in response to DNA damage, we examined the cellular response to genotoxic stress in viably-frozen ALL cells (n = 3 patients) or non-cancer bone marrow-derived stem cells (BMSC) (n = 2 donors)." (PMID 37989729, 2023).
cancer (continued). "However, the role of oncogenic PARP1 functions outside of DDR has been less well studied, and here we provide evidence that PARP1 promotes CCA growth and metastasis in vivo, suggesting that PARP1 could also be a more general target in this cancer type." (PMID 37821462, 2023). "The most validated hypothesis is that cancer cells and non-cancer cells which are subjected to long-term oxidative stress, extensive DNA damage, or inflammatory conditions, up-regulate PARP-1 to repair mildly damaged DNA and harbour carcinogenetic mutations that promote tumour growth." (PMID 35158955, 2022). "As there are multiple agents on the market that inhibit paralogues, such as trametinib (MEK1, MEK2) and PARP inhibitors (PARP1, PARP2), each of the 27 gene pairs we identified could be considered as targets for therapy development if follow-up studies can identify selectivity for cancer cells." (PMID 33637726, 2021). "In profile 25, PARP1, as the main poly (ADP-ribose) polymerase molecule, could influence many processes, including genome maintenance, replication, transcription, and chromatin remodelling, which makes it a central regulatory hub in many cancer-relevant processes." (PMID 34966737, 2021). "However, we doubt whether this may be sufficient to counteract an increased activity of NAD+-degrading enzymes, for instance poly (ADP-ribose) polymerase 1 (PARP1) and CD38, due to inflammatory conditions induced by cancer cell metabolism itself as well as by treatment." (PMID 34835963, 2021). "The cleavage of pro-caspases and PARP-1 in the PRMT5 knockdown A549-CFLARL cells was weaker than that in the control knockdown cells after treatment with doxorubicin, suggesting that CFLARL could prevent cancer cells from PRMT5-knockdown-enhanced apoptosis after doxorubicin treatment." (PMID 30736843, 2019). "Our data show that cancer-associated mutations at these sites involving a loss of positive charge destabilize autoinhibitory interactions between the macro domain and the ATPase motor of ALC1 and yield elevated ATPase and nucleosome remodeling activities independent of activation by PARP1/NAD+." (PMID 29220652, 2017). "However, the exact effects of PARP1 on transcription and DNA methylation pathways at specific genes are complicated and obscure, indicating the manipulation of gene transcription via PARP-1 in tumors is still too immature and tender for clinical cancer therapy." (PMID 28991194, 2017). "The increased incidence of lymphopenia and cancer in CKD patients may be due (at least in part) to (i) lengthy, continuous exposure of the cell’s genome to endogenous DNA-damaging compounds and (ii) hypersensitivity to DNA-damaging agents in general as a result of PARP-1 inhibition." (PMID 27854278, 2016). "To check whether PARP-1 has any role in the regulation of metastatic nature of cancer cells after treatment with carbon ion exposure, we looked into the activities and expression of two major matrix metalloproteinases, MMP-2 and MMP-9, which are highly activated during cancer metastasis." (PMID 27659937, 2016). "Both SIRT1 and PARP1 play an intimate role in the regulation of genomic stability, and continued work is necessary for the understanding of the specific contexts in which modulators of SIRT1 and PARP1 activity may be appropriate as therapeutics for cancer and metabolic disorders." (PMID 24360018, 2013). "For instance, PARP1 inhibition suppresses BRD7 PARylation and its ubiquitination degradation, sensitizing BRD7‐positive, rather than BRD7‐negative cancer cells to chemotherapeutic drugs." (PMID 36909172, 2023).